INS (insulin)
Diseases named in the same sentence as INS in open-access papers (continued):
Sharing a sentence is not in itself a finding about the gene and the disease.
viral infection (99 papers, 2009 to 2025). "The risk is higher in children who omit insulin, who had diarrhea and vomiting during viral infections, and in puberty mostly with alcohol consumption." (PMID 35630055, 2022). "Emerging evidence indicates that insulin signaling is engaged in various viral infections, such as those caused by Chronic hepatitis C virus (HCV), Zika virus, and influenza virus." (PMID 34207166, 2021). "In general, insulin secretory function is tightly linked to changes in ATP concentrations, but little is known about how ATP concentrations are regulated during viral infection and/or antiviral responses." (PMID 23383295, 2013). "Similarly, hsa-mir-15a-5p has been implicated in regulating insulin sensitivity and inflammatory responses, further supporting its potential role in the pathophysiology of T2D and viral infections." (PMID 40370100, 2025). "Similarly, IFNγ has been demonstrated to cause insulin resistance in muscle cells, promoting pancreatic insulin secretion during viral infections." (PMID 39768214, 2024). "Various factors such as genetic inheritance, viral infection, unhealthy lifestyle, and other physical or chemical damages lead to β-cell destruction, impaired insulin secretion, and loss of peripheral tissue insulin sensitivity, finally resulting in a high blood glucose level." (PMID 34764939, 2021). "Both bacterial and viral infections have been associated with reduced insulin sensitivity and similar to our findings, risk for development of IR may be independent of exposure to certain ARV medications or classes of medications (e.g. PIs)." (PMID 35538928, 2019). "To determine whether the increased lifespan and lowered rate-of-senescence under reduced adulthood insulin signalling were associated with a cost to reproduction under viral infection, we measured age-specific and total lifetime reproduction in the same individuals that were assayed for survival." (PMID 38589671, 2024). "Interestingly, also 10 out of 25 T2DM patients were positive for enteroviral capsid protein vp1 expression, suggesting that viral infections may contribute to beta cell loss and insulin dependency in T2DM as well." (PMID 25956355, 2015). "These exciting findings show that the mechanism responsible for the inhibition of insulin secretion by NO also functions to protect β-cells during a viral infection." (PMID 41067639, 2025). "Viral infection leads to a marked reduction in pancreatic insulin levels and secretory capacity, alongside β-cell apoptosis." (PMID 40564201, 2025). "Prior studies have shown that single components, such as insulin or glucose, can modulate virus infection." (PMID 41472722, 2025). "In the pathogenesis of viral infections, metabolic responses such as decreased insulin sensitivity, increased hepatic gluconeogenesis, and accelerated lipolysis are involved under the influence of proinflammatory cytokines (e.g., TNF-α, IL-6)." (PMID 41150364, 2025). "Pathway analysis demonstrated spaceflight induced changes in insulin resistance, estrogen signaling, stress response, and viral infection." (PMID 38862620, 2024). "In the D. melanogaster antiviral response, insulin feeding activates the MAPK/ERK to restrict viral infection." (PMID 38921161, 2024). "The role of NMU as pro-viral during WNV infection and in mammalian immunity should be studied further, specifically how it signals during virus infection and acts a suppressor of insulin secretion and the insulin-mediated antiviral response." (PMID 38921161, 2024). "STs are multifunctional chemicals that have several roles in the neurological system, immunological system, bacterial and viral infections, hemostasis and thrombosis, insulin production, and hemostasis." (PMID 38943216, 2024). "Evidence for this postulate further stems from our studies in Ubxn9−/− cells whereby constitutive GLUT4 trafficking continued to strengthen its interaction with RLRs following subsequent AKT activation (e.g., insulin, virus infection)." (PMID 38883790, 2024).
viral infection (continued). "Induction of a transient insulin resistant, hyperinsulinemic state by a viral infection has been proposed as a physiological response to promote anti-viral CD8+ effector T cell activity." (PMID 36992811, 2023). "Many reports have now demonstrated that the ERK pathway is induced by virus infection in mosquitoes, serves an antiviral role, and, importantly, can be enhanced by the mammalian insulin present in a bloodmeal." (PMID 37509194, 2023). "Consistently, as we will discuss below, viral infections induce pro-inflammatory cytokine signaling which acutely reduces systemic insulin sensitivity in order to boost available insulin to immune cells for optimal anti-viral immunity." (PMID 36992811, 2023). "Studies have shown that miRNAs are involved in regulating physiological processes, such as insulin secretion, tumor formation, bacterial infection, and viral infection." (PMID 34602057, 2021). "It is known that viral infection can affect insulin signaling pathways as it is modulated by the production of interferon-ɣ, a common molecule present in viral infection." (PMID 34513323, 2021). "To further link metabolic responses and inflammation, we assessed insulin signaling related genes, observing that viral infection significantly decreased transcriptional levels of igf1 and its receptor igf1r in the liver of IPNv challenged fish." (PMID 34768822, 2021). "These authors finally suggested that the immune response to HHV8-infection was able to stimulate cell metabolism by inducing an increased insulin and glucose uptake in virus infected cells, as generally happens in several tumour-viral infections." (PMID 32168836, 2020). "Viral infection and subsequent IFN-α/β synthesis can lead to ER stress within insulin-producing β-cells causing neo-epitope generation, activation of β-cell-specific autoreactive T cells, and β-cell destruction." (PMID 32635205, 2020). "For TGEV Miller, incubation with intestinal contents, porcine insulin, and Wnt agonist significantly increased the virus infection from 1.0 ± 0.3% to 3.6 ± 0.9%, 3.2 ± 0.9% and 3.0 ± 0.5%, respectively." (PMID 32260595, 2020). "Because insulin is ingested during the bloodmeal, a recent study has shown that vertebrate insulin is able to regulate the type of innate immune response that occurs during viral infection in insect vector hosts." (PMID 31921210, 2019). "This is the first study in which we transfected PIC into insulin-producing cells differentiated from human iPS cells to establish a human viral infection model." (PMID 26659307, 2015). "The INS and INr peptides were also able to support high productive virus infection in LEDGF/p75-knockdown cells, probably due to their ability to promote an increase in viral cDNA integration events in these cells." (PMID 20678206, 2010). "Suggested environmental triggers of T1D have included viral infections and exposure to exogenous proteins, such as bovine insulin from cow's milk." (PMID 20221424, 2010). "It is known that during virus infection, insulin synthesis increases as part of the stress response." (PMID 19888425, 2009). "Since [Ca2+]cyto elevation could happen under many conditions, for example, virus infection and insulin signaling, the regulation of lysosome pH by PERK may widely exist." (PMID 40701245, 2025). "Activators of PRK2 could potentially mimic its role in nutrient sensing or insulin sensitization, whereas allosteric inhibitors may find utility in the treatment of cancer or viral infections." (PMID 39002682, 2024). "How (and if) Upd ligands are activated in response to viral infection is still unknown, but it may be mediated by insulin signaling (see Section 6)." (PMID 37509194, 2023). "Thus, viral infections should be minded among pregnant women whose insulin sensitivity is already physiologically reduced." (PMID 37927616, 2023).
viral infection (continued). "Interestingly, the insulin response to high glucose stimulation was maintained following Poly (I:C) transfection, despite the inflammatory response mimicking a viral infection (p = 0.042)." (PMID 36560784, 2022). "Furthermore, during a viral infection, inflammatory pathways were differently altered in insulin-resistant participants with respect to insulin-sensitive individuals." (PMID 35010920, 2021). "Although the change in insulin level induced by viral infection was not yet reported in insects or even linked to antiviral immunity prior to this report, the decrease in insulin secretion was found to be common in mammals after viral infection." (PMID 33708207, 2021). "Our study sheds new light on the intrathymic regulation of Igf2 transcription during CV-B4 infections and supports the hypothesis that a viral infection can disrupt central self-tolerance to insulin by decreasing Igf2 transcription in the thymic epithelium." (PMID 33672010, 2021). "Also, SARS‐CoV‐2 facilitated impaired insulin secretion through ACE2 in pancreatic endocrine cells, meanwhile diabetic patients are susceptible to viral infections, causing cytokine storms, and worsening clinical presentation." (PMID 32893398, 2020). "First, we confirmed that viral infection attenuated insulin signaling in 3D-keratinocytes." (PMID 31581253, 2019). "In a retrospective study from a single center in Saudi Arabia, the predominant precipitating cause of DKA were viral infections and non-compliance to the insulin regimen of the diagnosed diabetic cases." (PMID 31824422, 2019). "A recent personal-omics analysis showed transcriptional modulation of genes in pathways involved in glucose regulation of insulin secretion occurred shortly after viral infection, and was predicted as involved in elevation of glucose and HbA1c in a Caucasian subject." (PMID 25868721, 2015). "In order to explore whether NR4A3 has an effect on insulin expression in pancreatic beta cells, viral infection was used to produce stable or transient expression of NR4A3 in the MIN6 cell line." (PMID 24638142, 2014). "However, in the presence of INrs and INS peptides, relatively high levels of viral cDNA integration as well as productive virus infection were obtained following infection by a wild type (WT) HIV-1 of LEDGF/p75-knockdown cells." (PMID 20678206, 2010). "Second, we analyzed the effect of insulin treatment on viral infection." (PMID 20657771, 2010). "However, our previous laboratory study found that insulin treatment might significantly worsen viral infections by elevating interleukin-6 levels and the ratio of severe complications to death." (PMID 38755442, 2024). "Network analysis also revealed links to insulin and glucose regulation, which is of importance for diabetic patients; however, insulin can also regulate immune cell function during viral infection, particularly in T cells, and thus may play a role in immune responses." (PMID 34230210, 2021). "In addition, diabetic patients might need additional administration of insulin or secretagogues, as the viral infection can stimulate cortisol release and thus increase of blood glucose levels." (PMID 32825068, 2020). "Furthermore, we extended our study to include insulin-producing cells differentiated from human induced pluripotent stem (iPS) cells to establish a viral infection model of human pancreatic beta cells and to evaluate the anti-apoptotic effect of Ex4 on human insulin-producing cells." (PMID 26659307, 2015). "However, whether the upregulation of ACE2 induced by activation of the FGF7-FGFR pathway would be a beneficial for insulin secretion or potentially promote viral infection during SARS-CoV-2 infection remained uncertain and investigated in the following section." (PMID 38654010, 2024). "Pancreas sections of EV-positive cases (both DiViD and LPN) were stained for insulin and for enteroviral VP1 to assess the sites of viral infection." (PMID 35953727, 2022).
viral infection (continued). "We show that the viral infection activates an integrated stress response, including activations of serine kinases such as PKR and PERK, which induce IRS-1 serine phosphorylation and insulin resistance." (PMID 33648564, 2021). "Additionally, two viral infections have been linked to NODAT: hepatitis C virus, which could favor insulin resistance and generate a direct harmful effect on pancreatic cells, and CMV infection, which enhances cytokine-mediated pancreatic islet injury and apoptosis." (PMID 32908503, 2020). "Polyinosinic:polycytidylic acid transfection can mimic viral infection, and Exendin-4 exerted an anti-apoptotic effect both in MIN6 and insulin-producing cells from human induced pluripotent stem cells." (PMID 26659307, 2015). "In conclusion, we demonstrated that PIC transfection can mimic viral infection both in MIN6 cells and insulin-producing cells differentiated from human iPS cells." (PMID 26659307, 2015). "We exploited virus infection techniques to induce expression of NR4A3 or three deletion mutants, and determined expression of insulin and insulin regulatory genes in MIN6 cells." (PMID 24638142, 2014). "Moreover, the GLUT4-RIG-I interaction strengthened over time upon stimulation with insulin (in adipocytes and C2C12 myocytes), 3p-hpRNA and virus infection in WT myocytes." (PMID 38883790, 2024). "C2C12 cells without virus infection were subjected to serum starvation for 4 h and this was followed by treatment with 100 nM insulin for 0 (lane 13) and 60 min (lane 14)." (PMID 28106162, 2017). "In conclusion, our results suggest that downregulation of insulin signalling in C. elegans is a promising strategy to boost anti-viral defence and improve survival under viral infection, without reproductive costs, in addition to its beneficial role in anti-bacterial resistance and healthy ageing." (PMID 38589671, 2024). "On this topic, it has been shown that simply infusing insulin to better glycemic control may not necessarily benefit all patients with viral infection." (PMID 36992811, 2023). "Many factors can affect blood glucose levels such as exercise, viral diseases, stress, and hormonal effects, which are not related to periods of food intake or insulin bolus but might be present during the time that basal insulin must cover." (PMID 33204261, 2020). "Since virus infection may influence cell differentiation efficiency and interfere with many signalling pathways, we first tested whether the infected cells (negative control) are still responsive to insulin treatment." (PMID 30948776, 2019). "Thus, viral infection at 10 MOI of INS 832/13 cells induces some cell toxicity, with defective GIIS but not cell death or altered insulin content." (PMID 24130841, 2013). "The relatively low efficiency of lenti-virus infection (20.5±7.4% of KRT+ cells), cannot rule out the possibility that additional cells in the culture could give rise to insulin producing cells." (PMID 22028850, 2011).
periodontitis (95 papers, 2009 to 2026). An acute or chronic inflammatory process that affects the tissues that surround and support the teeth. "Additional medications, including antidepressants, oral hypoglycemic agents, calcium channel blockers, insulin, diuretics, and anticonvulsants, have also been implicated in increasing the likelihood or severity of periodontitis in various studies." (PMID 41302318, 2025). "Oxidative stress, which is elevated in periodontitis, can also impair insulin signaling by causing damage to the insulin receptor and other key components involved in glucose metabolism." (PMID 40136728, 2025). "We examined the causal association of periodontitis with glycemic traits (HbA1C, fasting glucose, and fasting insulin) and T2DM using an MR study." (PMID 34899852, 2021). "WAT mediated chronic inflammation in diabetics not only contributes to more severe periodontitis, but also is implicated in determining insulin resistance through the production of pro-inflammatory cytokines." (PMID 24836538, 2014). "Additionally, the chronic inflammation associated with periodontitis induces oxidative stress, further disrupting insulin action and contributing to hyperglycemia." (PMID 40283848, 2025). "We found that in agreement with our hypothesis, insulin and hypoglycemic agents demonstrated a disease severity-dependent association when comparing periodontitis staging." (PMID 39157205, 2024). "Insulin and oral hypoglycemic agents were associated with Grade C periodontitis because the current classification of periodontal disease includes HbA1c levels and smoking status as modifying factors that should be considered when determining the grading process." (PMID 39157205, 2024). "This may be due to higher exposure to competing strains, such as pathogenic F. nucleatum strains that induce periodontitis and enhance insulin resistance." (PMID 37666816, 2023). "Periodontitis and impaired wound healing in diabetes are linked to insulin resistance and high blood sugar levels, both of which have been associated with the specific decline in insulin-induced activation of the PI3K/Akt pathway in the gingiva." (PMID 37895050, 2023). "In animal models, periodontitis induction is associated with hyperinsulinemia, suggesting a direct impact of periodontal bacteria on the function of pancreatic β-cells, the only known source of circulating insulin." (PMID 35327570, 2022). "However, the associations for liability to periodontitis with fasting glucose and fasting insulin were similar to those for HbA1c." (PMID 34899852, 2021). "The translocation of bacteria and bacterial products associated with periodontitis, such as lipopolysaccharides, into the bloodstream can induce a systemic inflammatory process, resulting in elevated levels of acute-phase and oxidative stress biomarkers, with repercussions on insulin action." (PMID 40667952, 2025). "Additionally, PD management has been implicated in insulin levels control with periodontal treatment allowing the alleviation of high glycemic levels, and therefore uncontrolled periodontitis may indirectly impact on PCOS clinical status." (PMID 32585861, 2020). "It is commonly suggested that periodontitis influences systemic health through the activities of cytokines and/or LPS that originate in the gingiva and enter the systemic circulation thereby reaching target organs to cause insulin signaling impairment, i.e. insulin resistance (IR)." (PMID 26317345, 2015). "Plasma EVs from patients with periodontitis impaired insulin signaling and glucose uptake in hepatoma cells, exacerbating insulin resistance in type 2 diabetes." (PMID 41153802, 2025). "Severity of periodontitis are increased and advanced in DM; and severe periodontitis in turn elicits adverse effects on DM through impairing insulin actions results from systemic microinflammation." (PMID 40521359, 2025).